S1PR1 (sphingosine-1-phosphate receptor 1)
Diseases named in the same sentence as S1PR1 in open-access papers (continued):
Sharing a sentence is not in itself a finding about the gene and the disease.
injury (5 papers, 2014 to 2025). Damage inflicted on the body as the direct or indirect result of an external force, with or without disruption of structural continuity. "Genetic and pharmacological inhibition of S1PR1 by selective antagonists in distinct chemical classes decreased and counteracted neuropathic pain in mice models of traumatic nerve injury." (PMID 31197114, 2019). "Notably, S1PR1 has been shown to be upregulated in various acute inflammatory conditions, including stem cells of myeloid leukemia and LPS-induced acute lung injury, suggesting the pivotal role of S1PR1 in maintaining acute inflammation." (PMID 39833165, 2025).
myeloma (5 papers, 2016 to 2025). "S1PR1 depleted myeloma cells retained full CXCL12 responsiveness while CXCR4 depleted myeloma cells were unable to induce CXCL12-stimulated cell adhesion or transendothelial migration after S1P stimulation." (PMID 35756630, 2022). "In conclusion, a total of 393 DEGs were identified between osteocytes co-cultured with and without myeloma cells, and KLF4, IRF8, EGF, EGR1, S1PR1, C3AR1, and NPY1R might be involved in osteocyte cell apoptosis induced by MM cells." (PMID 27405725, 2016).
prostate carcinoma (5 papers, 2013 to 2023). A carcinoma that arises from epithelial cells of the prostate gland. "Results from the analysis indicated that expression levels of STAT3-regulated pro-angiogenic genes, such as S1PR1, MMP9 and HIF1a, correlated with the density of tumor-infiltrating B cells in human prostate cancers." (PMID 23734190, 2013).
atopic dermatitis (4 papers, 2020 to 2024). "The S1P–S1PR1 axis is also associated with atopic dermatitis, showing decreased S1PR1 protein expression in basophils in patients with atopic dermatitis." (PMID 37830566, 2023).
diffuse large B-cell lymphoma (4 papers, 2014 to 2022). "In tumor cells, S1PR1 was identified as a potential target to block STAT3 signaling in activated B cell-like diffuse large B-cell lymphoma." (PMID 36361531, 2022). "We analyzed S1PR1/STAT3 pathway activation using immunohistochemistry in rituximab-treated diffuse large B-cell lymphomas (DLBCL; N = 103)." (PMID 25472725, 2014).
Hodgkins lymphoma (4 papers, 2014 to 2023). A heterogeneous group of malignant lymphoid neoplasms of B-cell origin characterized histologically by the presence of Hodgkin and Reed-Sternberg (HRS) cells in the vast majority of cases. "Hodgkin lymphoma and mantle cell lymphoma showed S1PR1 expression in cell lines or tissues, suggesting potential biologic roles for S1PR1 in this context." (PMID 25472725, 2014). "In Hodgkin's lymphoma, 7/56 cases showed staining for S1PR1." (PMID 27239439, 2016).
lung disease (4 papers, 2017 to 2025). "Overall, these findings support the concept that S1PR1 acts as a modifier influencing the severity of CF lung disease and shaping the epithelial response to bacterial infection." (PMID 41305383, 2025). "S1PR1 has been found to be downregulated in human pulmonary diseases such as COPD and induction of the S1PR1 receptor activity increases survival and vascular permeability." (PMID 31906427, 2020).
neuroblastoma (4 papers, 2013 to 2023). Neuroblastoma (NB) is the most common solid, extracranial childhood tumor. "Similarly, the treatment of neuroblastoma cell lines with an antagonist of S1PR1 significantly increased the susceptibility of cancer cells to etoposide." (PMID 35954425, 2022). "Next, they prepared an S1PR1 knockdown in neuroblastoma cells by shRNA, which enhanced chemotherapeutic agent etoposide-induced apoptosis in neuroblastoma cell lines." (PMID 35954425, 2022). "The expression of S1PR1 has previously been reported to correlate to chemoresistance in neuroblastoma, and its abrogation significantly reduced the observed resistance." (PMID 33753779, 2021).
pancreatic cancer (4 papers, 2019 to 2025). "Likewise, S1PR1 signaling inhibition treatment resulted in inhibition of cell growth in pancreatic cancer cells via STAT3 pathway." (PMID 31438989, 2019). "Interestingly, S1PR1 was also one of the target genes of STAT3 and S1PR1/STAT3 formed a positive feedback loop, which might play important roles in the progression of pancreatic cancer." (PMID 31438989, 2019).
rheumatic heart disease (4 papers, 2021 to 2025). An autoinflammatory condition following an infection with Group A Beta Hemolytic Streptococcus (GABHS), in which the heart is attacked by antibodies formed in reaction to a recent GABHS infection. "Additionally, in rheumatic heart disease, overexpression of S1PR1 reduces p-STAT3 levels and Th17-associated cytokines RORγt, IL-6 and IL-17." (PMID 37858140, 2023). "In rheumatic heart disease, miR‐155 aggravated the valve injury through S1PR1, SOCS1/STAT3 and IL‐6/STAT3 signalling pathways." (PMID 33664937, 2021). "Therefore, LINC00707 can reduce myocardial damage and fibrosis in female rheumatic heart disease rats via modulating miRNA-145-5p/S1PR1." (PMID 39256355, 2024). "Studies have found that LINC00707 reduces rheumatic heart disease (RHD) myocardial fibrosis and regulates immune dysfunction through the miR-145-5p/S1PR1 pathway." (PMID 40264452, 2025).
Thrombocytopenia (4 papers, 2013 to 2022). A reduction in the number of circulating thrombocytes. "Activation of S1PR1 prompts the release and circulation of new blood platelets to prevent blood loss during injury, and mice lacking S1PR1 develop severe blood clotting (thrombocytopenia)." (PMID 33003377, 2020). "A recent investigation uncovered a novel function of S1PR1 as the critical regulator of efficient thrombopoiesis; mice lacking the S1P receptor S1PR1 developed severe thrombocytopenia, which suggests new therapeutic approaches for patients with this disease." (PMID 24073762, 2013).
Allergy (3 papers, 2011 to 2023). An allergy is an immune response or reaction to substances that are usually not harmful. "Basophils, which are involved in various allergic diseases, express S1PR1-4." (PMID 37830566, 2023). "Mast cells, which comprise one of the most critical cell types in allergic diseases, express S1PR1, S1PR2, and S1PR4, but not S1PR3 or S1PR5." (PMID 37830566, 2023).
autoimmune thyroiditis (3 papers, 2021 to 2025). "Notably, the expression of S1PR1 is increased in T CD4+ cells in autoimmune thyroiditis, triggering the activation of STAT3 signaling through S1PR1/mTOR/PSer727STAT3 and S1PR1/JAK2/PTyr705STAT3 cascades." (PMID 34981746, 2022).
bone cancer (3 papers, 2018 to 2024). A primary or metastatic malignant neoplasm affecting the bone or articular cartilage. "Likewise, one study found that intrathecal fingolimod reduces bone cancer pain, and while analgesia was attributed to effects on S1PR1 in glia, some of the benefits may be due to S1PR3 signaling in DRG neurons." (PMID 29561262, 2018).
cardiomyopathy (3 papers, 2020 to 2021). A disease of the heart muscle or myocardium proper. "Hence, individuals who are heterozygous for predicted loss‐of‐function S1PR1 alleles have been observed at very low frequency, and cardiomyopathy exome/genome sequencing studies may reveal additional S1PR1 variants that disrupt S1P1 function." (PMID 34618403, 2021). "Cardiomyocyte-restricted deletion of S1PR1 shows progressive cardiomyopathy and premature death due to impaired activity of sarcolemmal Na+/H+ exchange and increased Ca2+ sensitivity." (PMID 34222276, 2021). "Animal models has demonstrated that the deletion of cardiac sphingosine 1-phosphate receptor 1 could lead to the incident of cardiomyopathy and HF." (PMID 32299366, 2020).
esophageal squamous cell carcinoma (3 papers, 2019 to 2024). Esophageal squamous cell carcinoma (ESCC) is a type of esophageal carcinoma (EC) that can affect any part of the esophagus, but is usually located in the upper or middle third. "S1PR1 inhibits apoptosis, activating MAPK signaling and reducing ROS levels in AML cells and inducing proliferation in HCC and esophageal squamous cell carcinoma." (PMID 39791702, 2024).
fibrosis (3 papers, 2020 to 2025). the formation of excess fibrous connective tissue in an organ or tissue in a reparative or reactive process. "By contrast, the adult survivors of embryonic cardiomyocyte S1pr1 deletion showed increased cardiac fibrosis as compared with littermate controls." (PMID 34618403, 2021). "Five variable multi-omics analysis provided more granular understanding of the core differences in expression between groups, with ELOVL2, LIPK, LAMA3, and lncRNAs partnered with UHRF1BP1L and S1PR1 found to most reliably discriminate the control and fibrosis groups." (PMID 40040391, 2025). "Finally, cardiomyocyte S1pr1 mutant mice demonstrated increased cardiac fibrosis that correlated with QRS prolongation." (PMID 34618403, 2021).
glaucoma (3 papers, 2023 to 2025). Increased pressure in the eyeball due to obstruction of the outflow of aqueous humor. "Our findings suggest that S1PR1 is a potential therapeutic target for neuroprotection of RGCs in glaucoma." (PMID 36520045, 2023). "Our recent study showed that mice treated orally with siponimod drug exerted neuroprotection via modulation of neuronal S1PR1 in experimental glaucoma." (PMID 36520045, 2023). "Conversely, deletion of S1PR1 in RGCs significantly increased the apoptotic cells in the ganglion cell layer in glaucoma and diminished the neuroprotective effects of siponimod treatment on Akt/Erk1/2 activation, c-Jun/Bim cascade, and Bad phosphorylation." (PMID 36520045, 2023).
Hyperglycemia (3 papers, 2021 to 2025). An increased concentration of glucose in the blood. "Therefore, S1P can mediate hyperglycemia-induced dysfunction of HUVECs through binding to S1PR1 and S1PR2." (PMID 36229882, 2022). "A series of biological activities of endothelial cells mediated by S1PRs can be regulated by S1P, of which S1PR1 and S1PR2 play a key role in hyperglycemia-induced endothelial cell dysfunction." (PMID 36229882, 2022). "S1PR1 and S1PR2 were found to be involved in endothelial vascular dysfunction under high-glucose conditions, where S1PR1 protein and mRNA levels decreased during hyperglycemia, and S1PR2 levels increased." (PMID 41301404, 2025).
lung adenocarcinoma (3 papers, 2020 to 2024). A carcinoma that arises from the lung and is characterized by the presence of malignant glandular epithelial cells. "Low expression of S1PR1 was associated with worse overall survival (OS) in male and female patients with lung adenocarcinoma (P < 0.05)." (PMID 32799825, 2020). "In this study, we aim to explore the role and downstream signaling pathways of S1PR1 in the malignant biological functions of lung adenocarcinoma (LUAD)." (PMID 39551792, 2024). "Moreover, the inhibitory effect of S1PR1 on tumor growth was attenuated by FOXA1 overexpression, suggesting that the role of FOXA1 in mediating the effects of S1PR1 on lung adenocarcinoma cell proliferation." (PMID 39551792, 2024). "Gene expression data of breast invasive carcinoma (BRCA), lung adenocarcinoma (LUAD) and lung squamous cell carcinoma (LUSC) in TCGA were downloaded and S1PR1 mRNA expression level was compared between tumor and normal tissue." (PMID 32799825, 2020). "Significant differences in the expression of AURKA and S1PR1 between normal and lung adenocarcinoma (LUAD) tissues were found in the GEPIA2 database; Western blot showed that OSU-2S could affect p-AURKA and S1PR1 protein expression." (PMID 38794152, 2024).
neuropathic pain (3 papers, 2022 to 2026). Chronic pain caused by damage to nerve fibers. "Although early studies reported that activating S1PR1 has analgesic effects, emerging evidence implicated genetic and pharmacological inhibition of S1PR1 could alleviate mechanical and thermal hyperalgesia in various neuropathic pain models." (PMID 35144528, 2022). "Studies in neuropathic pain have found that inhibition of S1PR1 can significantly reduce the activation of astrocytes and microglia in the spinal dorsal horn." (PMID 35144528, 2022).
nonalcoholic steatohepatitis (3 papers, 2019 to 2023). "In a recent study, researchers found that FTY720 (a broad-spectrum S1PR modulator against S1PR1/3/4/5) ameliorates non-alcoholic steatohepatitis in mice by reducing hepatic macrophage accumulation." (PMID 31546702, 2019). "Among them, S1PR1 controls the expression of IL-1β in response to Newcastle disease virus by modulating the NLRP3/caspase-1 inflammasome pathway and enhances inflammation and fibrosis in the kidney, while S1PR4 promotes nonalcoholic steatohepatitis by activating NLRP3 inflammasomes." (PMID 38003456, 2023).
Parkinson disease (3 papers, 2022 to 2025). A progressive degenerative disorder of the central nervous system characterized by loss of dopamine producing neurons in the substantia nigra and the presence of Lewy bodies in the substantia nigra and locus coeruleus. "S1pr1 and S1pr5 are expressed by several cell types of the central nervous system, including microglia, which produce pro-inflammatory cytokines and molecules, and are closely related to Parkinson’s disease." (PMID 39451223, 2024).
preeclampsia (3 papers, 2017 to 2021). Preeclampsia is a hypertensive disorder of pregnancy that is characterized by new-onset hypertension with proteinuria presenting after 20 weeks of gestation, and depending on mild or severe forms may initially present with severe headache, visual disturbances, and hyperreflexia. "For example changes in miR-125b-1-3p which target S1PR1 are common in the pathogenesis of inflammatory diseases such as preeclampsia." (PMID 34001212, 2021). "Thus, the inverse regulation of S1PR1 and S1PR2 expression in chorionic arteries might explain, at least in part, the vascular dysfunction reported in preeclampsia, including a heightened placental vascular resistance." (PMID 32033121, 2020).
schizophrenia (3 papers, 2014 to 2022). A major psychotic disorder characterized by abnormalities in the perception or expression of reality. "If S1PR1 PET reveals biologically distinct subtypes of schizophrenia, the clinical relevance is that PET study can be used to stratify patient cohorts in therapeutic trials of new drugs." (PMID 35350429, 2022). "S1PR1 PET will potentially complement for investigating neuro-inflammation in schizophrenia with other currently used ligands, such as Translocator protein (18 kDa) (TSPO) PET." (PMID 35350429, 2022). "For the two types of schizophrenia patients, it appeared that only Type 2 schizophrenia has significantly upregulated S1PR1 compared to Type 1 schizophrenia and controls, respectively." (PMID 35350429, 2022). "Overall ARG S1PR1 intensity mean (standard error) was 76.10 (4.66) for controls, 71.44 (5.87) for Type 1 schizophrenia, and 91.91 (5.87) for Type 2 schizophrenia." (PMID 35350429, 2022). "AGR S1PR1 is highly expressed in Type 2 schizophrenia in all three measures compared to Type 1 schizophrenia and controls." (PMID 35350429, 2022). "Previous literature and our present findings taken together thus suggest that there is great potential for studying neuro-inflammation (or related mechanisms) in schizophrenia with in vivo S1PR1 PET." (PMID 35350429, 2022). "We hypothesized that S1PR1 protein expression will show elevations in Type 2 schizophrenia compared to Type 1 schizophrenia and controls consistent with Bowen's S1PR1 mRNA findings." (PMID 35350429, 2022). "Thus, the present ARG findings and previous reports taken together indicate that both S1PR1 protein and S1PR1 mRNA upregulate in DLPFC only in a subset of schizophrenia." (PMID 35350429, 2022). "Immunostaining of S1PR1 was performed in control and schizophrenia samples." (PMID 35350429, 2022). "ARG analysis of S1PR1 was performed in control and schizophrenia DLPFC samples." (PMID 35350429, 2022). "Overall, these findings strongly suggest S1PR1 might serve as a candidate target in schizophrenia subtypes with PET where protein is the target." (PMID 35350429, 2022). "In this study, we evaluated the expression of S1PR1 and distribution of S1PR1 specific tracer [3H]CS1P1 in human DLPFC tissues from normal control, Type 1 and Type 2 schizophrenia subjects." (PMID 35350429, 2022). "Lastly, it remains to be investigated S1PR1 protein and S1PR1 mRNA expressions in other brain regions besides DLPFC of controls and Type 1 and Type 2 schizophrenia patients." (PMID 35350429, 2022). "The present study examines the differential expression of S1PR1 in the DLPFC of Type 1 and Type 2 schizophrenic patients at the protein level as a preliminary step toward the use of PET to distinguish Type 1 from Type 2 schizophrenia during life." (PMID 35350429, 2022). "One limitation is that present study as well as previous S1PR1 mRNA study cannot be used to identify schizophrenia Type 1 and Type 2 in vivo without PET and S1PR1 specific radiotracer." (PMID 35350429, 2022).
thyroid cancer (3 papers, 2013 to 2023). "In bladder and thyroid cancers, S1PR1 antagonist has been found to inhibit tumor proliferation and migration." (PMID 37828220, 2023). "However, S1PR1 expression was significantly higher in kidney renal clear cell carcinoma (KIRC) and thyroid carcinoma (THCA) than in adjacent normal tissues." (PMID 32799825, 2020).
Anxiety (2 papers, 2021 to 2024). Intense feelings of nervousness, tension, or panic often arise in response to interpersonal stresses. "Therefore anxiety-like behavior resulting from high dose FTY720 is associated principally with increased S1PR5 expression and to a lesser extent with decrease of S1PR1." (PMID 34177891, 2021).
B-cell lymphoma (2 papers, 2014 to 2016). "Thus, while S1PR1 is expressed at low levels in CLL lymph nodes as compared with normal B cells, increased expression of S1PR1 correlates with signal transducer and activator of transcription 3 (STAT3) activation and survival in B-cell lymphoma." (PMID 27800303, 2016).
brain infarction (2 papers, 2019 to 2021). Tissue necrosis in any area of the brain, including the cerebral hemispheres, the cerebellum, and the brain stem. "Results showed that DSCXQ intervention significantly reduced cerebral infarct size, ameliorated behavioral abnormality, inhibited the expression of Sphk1, S1PR1, CD62P, Bax, Cleaved Caspase-3, while increased the level of Bcl-2, and prevented neuronal apoptosis." (PMID 34026822, 2021).
brain injury (2 papers, 2016 to 2022). Acute and chronic (see also brain INJURIES, CHRONIC) injuries to the brain, including the cerebral hemispheres, CEREBELLUM, and brain STEM. "However, the potential association between S1PR1 and neurogenesis in hippocampus following traumatic brain injury (TBI) remains unknown." (PMID 28018679, 2016).
Chronic colitis (2 papers, 2019 to 2022). A chronic inflammatory disease of the large intestine (colon, cecum and rectum). "In contrast, the absence of miR-155 overexpression in the sigmoid colon of PSC-UC patients activated the Il-6/S1PR1 signalling pathway and imbalanced the IL17/FOXP3 ratio, which reinforces chronic colitis." (PMID 35563301, 2022). "Secondly, in the absence of miR-155 over-expression, the activated IL-6/S1PR1 signalling pathway reinforced chronic colitis in the sigmoid colon of PSC-UC patients." (PMID 35563301, 2022).
cutaneous melanoma (2 papers, 2020 to 2023). A primary melanoma arising from atypical melanocytes in the skin. "FAKi treatment robustly decreased TCF-4 binding to the CCND1 and C-myc promoters and induced a moderate decrease of WNT-11 and S1PR1 promoters, in concordance with the TCGA analysis in UM and cutaneous melanoma patients." (PMID 36797281, 2023). "Using a Venn diagram with TCF-4 co-expressed genes versus CDH5 co-expressed genes, 7 genes were robustly correlated, being S1PR1 the most prominent one not only in uveal melanoma but also in cutaneous melanoma." (PMID 36797281, 2023).